ALB (albumin)
Diseases named in the same sentence as ALB in open-access papers (continued):
Sharing a sentence is not in itself a finding about the gene and the disease.
influenza (continued). "The lung injury was assessed by measuring albumin concentration in BALF, as a marker of lung epithelial leakage, in PM-exposed influenza-infected mice treated with rIL22 or vehicle." (PMID 34906172, 2021). "Furthermore, we found that ONP-302 reduced the levels of MPO, albumin, IL-6, and TNF-α in the lungs of aged, influenza-infected mice." (PMID 35737459, 2022). "This could be attributable to the fact that NP vaccination significantly reduced the levels of inflammatory cytokines and chemokines and albumin, a marker of lung damage, in young but not aged lungs following influenza infection." (PMID 27177221, 2016). "Though no albumin/globulin ratio differences were observed when comparing influenza infection in ferrets, a marked decrease in the ratio occurred post-infection, which may be indicative of an overproduction of globulins." (PMID 23472182, 2013). "Moreover, serum albumin levels in bronchoalveolar lavage (BAL) samples of PBS and OP7 chimera DIP-treated mice were comparable, indicating that OP7 chimera DIP administration did not compromise lung integrity, which is otherwise typically observed in influenza-infected mice." (PMID 38017026, 2023). "However, the total protein, albumin, ALT, AST, LDL and antibody titer of influenza were not influenced." (PMID 33921779, 2021). "Thus, while NP vaccination generates a significant amount of NP-specific IgG in aged mice and protects from death due to influenza infection, it has no impact on viral load, BAL cytokines and chemokines or albumin levels." (PMID 27177221, 2016).
leukemia (34 papers, 1980 to 2025). A malignant (clonal) hematologic disorder, involving hematopoietic stem cells and characterized by the presence of primitive or atypical myeloid or lymphoid cells in the bone marrow and the blood. "Myelosuppressive toxicity is the main side effect of paclitaxel albumin nanoparticles, which can cause coagulation dysfunction and increase the risk of infection or even secondary leukemia, thus limiting its clinical use." (PMID 34109887, 2021). "The authors have characterized various modifications induced in human serum albumin and identified benzene-specific Cys34 adducts of reactive oxygen and carbonyl species, probably associated with the development of leukemia in patients." (PMID 29702613, 2018). "This adds to the literature of observed supra-linear responses associated with benzene exposure – see for example the response of benzene oxide-albumin adduct formation with benzene exposure, the dose related production of benzene metabolites and the relative risk of leukemia with benzene exposure." (PMID 24786086, 2014). "On multivariate analysis with laboratory variables included (749 patients), having leukemia, elevated ALC and reduced albumin were independently associated with 30‐day mortality attributable to COVID‐19." (PMID 38063366, 2023). "Leukaemia patients with low levels of serum albumin have a lower overall survival rate compared to patients with normal levels of serum albumin." (PMID 34835873, 2021). "In summary, we have demonstrated that DAS-loaded albumin NPs exhibited potent anti-leukemia activity as DAS." (PMID 27391073, 2016). "In our study, Albumin NPs entered leukemia cells efficiently, but exhibited little uptake by endothelial cells." (PMID 27391073, 2016). "The optimal SFM contained a RPMI1640+ epidermal growth factor (20 ng/ml), a basic fibroblast growth factor (20 ng/ml), a leukemia inhibitory factor (20 ng/ml), a B-27 serum-free supplement (20 μl/ml), and a bovine serum albumin (4 μg/ml)." (PMID 24188098, 2013). "The influence of human serum albumin (HA) on the biological effects of 13 chemotherapeutic agents was studied in vitro in the human leukaemia cell line MOLT-3." (PMID 7190020, 1980). "Albumin, which is primarily synthesized in the liver, not only serves as a marker of nutritional status but also has antiapoptotic signaling properties and participates in the transport and metabolism of chemotherapeutic agents in leukaemia." (PMID 41586228, 2025). "In addition, ALB has been identified as an independent prognostic factor following allo-HSCT in leukemia patients, capable of predicting long-term outcomes." (PMID 41438980, 2025). "Elevated CRP levels have been associated with several adverse disease features and a shorter leukemia-free survival, and albumin has been consistently shown to add additional prognostic information independently of DIPSS and several DIPSS-based prognostic scoring systems." (PMID 36900271, 2023). "Higher CRP levels are known to be associated with shortened leukemia-free and overall survival in univariate analyses, whereas for albumin, a prognostic value independent of several DIPPS-based scoring systems has been described previously." (PMID 36900271, 2023). "However, in leukemias with circulating myelocytes, this mechanism can be overwhelmed and lead to high levels of non‐albumin proteinuria from the lysozyme itself." (PMID 36051078, 2022). "We tested this hypothesis using monoclonal anti‐2,4,6‐dinitrophenyl immunoglobulin E/human serum albumin‐induced rat basophilic leukemia cells (RBL‐2H3 cells) and ovalbumin (OVA)‐induced AR in mice as in vivo and in vitro AR models, respectively." (PMID 34092045, 2021). "Hopefully, in the future we could also develop albumin NPs to selectively target leukemia cells and with less toxicity to normal leukocytes." (PMID 27391073, 2016). "Albumin NPs as a drug delivery system could improve the anti-leukemia efficacy of DAS through its cell-selective effects." (PMID 27391073, 2016).
leukemia (continued). "Therefore, albumin NPs could be a potential tool to improve anti-leukemia efficacy of DAS through its cell-selective effects." (PMID 27391073, 2016). "DAS released from albumin NPs can then bind to Src and BCR-ABL tyrosine kinases and inhibit their autophosphorylation along with their downstream targets leading to blockade of the oncogenic activities of leukemia cells." (PMID 27391073, 2016). "The albumin NPs are not designed to be more selective to leukemia cells than to normal leukocytes yet." (PMID 27391073, 2016). "We sensitized rat basophilic leukemia cells (RBLs) and mouse bone marrow-derived mast cells (BMMCs) with anti-dinitrophenol (DNP) immunoglobulin (Ig)E antibodies, stimulated them with exposure to DNP-human serum albumin (HSA), and then treated stimulated cells with 4-MU." (PMID 35268679, 2022).
schizophrenia (34 papers, 2010 to 2025). A major psychotic disorder characterized by abnormalities in the perception or expression of reality. "Several previous studies have reported that the abnormalities of TP, albumin, and globulin levels were implicated in the pathophysiology of psychiatric disorders, such as schizophrenia." (PMID 35958662, 2022). "Several acute phase proteins (A2M, C3, SERPINA1, and ALB), proposed as candidate biomarkers for schizophrenia, were also found to be associated with Parkinson's disease, Alzheimer's disease, and MDD." (PMID 26909022, 2016). "Albumin has antioxidant properties and current literature shows that patients affected by schizophrenia result to have lower albumin plasma levels than those with other psychotic disorders." (PMID 37436457, 2024). "Information on serum albumin and total cholesterol levels, lymphocyte counts, and body mass index during the stable stage of schizophrenia was collected to calculate the PNI, GNRI, and CONUT scores, according to their respective calculation criteria." (PMID 39495754, 2024). "Women affected by schizophrenia were found to have higher levels of pro-inflammatory markers compared to men, thus supporting our findings about gender differences in albumin plasma levels." (PMID 37436457, 2024). "Plasma antioxidants such as albumin, bilirubin, and uric acid were found to be quite low in schizophrenia patients compared to controls." (PMID 36831126, 2023). "The serum albumin level in patients with anti-NMDAR encephalitis was lower than that in patients with schizophrenia." (PMID 35874840, 2022). "For the patients with schizophrenia, serum albumin level was significantly lower and decreased albumin level was associated with the depressive score of Positive and Negative Syndrome Scale." (PMID 34983435, 2022). "In our study, serum concentration of Pb was found to be negatively correlated with metabolic biomarkers dysregulated in schizophrenia (liver function (i.e. ALB) and renal function (i.e., BUN))." (PMID 31671526, 2019). "Our meta-analysis pointed towards BBB impairment with increased albumin ratio and total protein in schizophrenia and affective disorders, and increased levels of albumin in affective disorders." (PMID 30116031, 2019). "The CSF/serum albumin ratio was increased in schizophrenia (1 study [54 patients]; SMD = 0.71; 95% CI 0.33–1.09) and affective disorders (4 studies [298 patients]; SMD = 0.41; 95% CI 0.23–0.60, I2 = 0%), compared to healthy controls." (PMID 30116031, 2019). "Nonetheless, CSF studies have revealed increased CSF/serum albumin ratio in individuals with schizophrenia and affective disorders indicating increased blood–brain barrier (BBB) permeability." (PMID 30116031, 2019). "Previous studies have demonstrated higher CSF/serum albumin ratio levels in patients with schizophrenia and bipolar disorder as well as a correlation to negative psychotic symptoms." (PMID 28039552, 2017). "Individual plasma antioxidants, albumin, bilirubin, and uric acid were also found to be lower in schizophrenia subjects." (PMID 25061527, 2014). "Significant reductions of plasma antioxidants (e.g., albumin, bilirubin and uric acid) are seen early in the course of schizophrenia and the present study, consistent with previous findings in patients with chronic schizophrenia." (PMID 20209081, 2010). "Previous studies have shown that plasma albumin levels were significantly lower in patients with first episode schizophrenia, suggesting that patients with schizophrenia may have greater oxidative stress responses." (PMID 38462585, 2025). "In addition, a Chinese study reported an inverse correlation between severity of depressive symptoms and levels of albumin in a sample of patients affected by schizophrenia in agreement with our results." (PMID 37436457, 2024). "Furthermore, Albumin-Globulin Ratio and serum creatinine levels significantly differed between the Miao and Han schizophrenia patients." (PMID 38594695, 2024).
schizophrenia (continued). "Furthermore, emerging evidence has suggested relationships between a lower serum albumin level with peptic ulcer disease and bowel disease in patients with schizophrenia." (PMID 38831863, 2023). "This may suggest that serum albumin and hemoglobin concentrations could also be used as markers of the clinical course in patients with schizophrenia." (PMID 38831863, 2023). "Notably, a previous study reported that Taiwanese inpatients with schizophrenia had lower serum albumin levels, suggesting that patients in the acute phase of disease have similar systemic responses, as also shown in other studies." (PMID 38831863, 2023). "There are also some reports that trace elements such as copper and zinc and ions such as calcium and magnesium, as well as serum albumin, may play a role in schizophrenia." (PMID 36256663, 2022). "There is also some evidence that aberrations in calcium signaling are associated with neurocognitive impairments and that lowered albumin may contribute to the severity of the phenome of schizophrenia." (PMID 36256663, 2022). "The potential of sweat as a source for new schizophrenia biomarkers was highlighted, since only 5 proteins [albumin (ALB), alpha-2-glycoprotein 1 (AZGP1), clusterin isoform 1 (CLU), apolipoprotein D precursor (APOD), and gelsolin isoform b (GSN)] were found in common between sweat and serum." (PMID 26909022, 2016). "Older Chinese patients with schizophrenia are more likely to be smokers, and while smoking may be associated with lower plasma albumin levels, it may help to prevent negative symptoms." (PMID 38462585, 2025). "Similar findings were shared in a study of 15 intensive care unit patients with albumin level below 4 g/dL treated with VPA for seizures, myoclonus, bipolar disorder, schizophrenia and refractory agitated behavior." (PMID 40051558, 2025). "Certain blood cell indexes such as neutrophil-lymphocyte ratio (NLR) and neutrophil-albumin ratio (NAR) have been used as biomarkers in various diseases, including schizophrenia." (PMID 38222994, 2024). "For instance, in a 2005 study albumin (ALB) and the RALDH gene ALDH1A1, which oxidises retinaldehyde to at-RA, were significantly downregulated in schizophrenia." (PMID 31666680, 2020). "The IgG ratio was increased in schizophrenia (1 study [54 patients]; SMD = 0.68; 95% CI 0.30–1.06), whereas the IgG Albumin ratio was decreased (1 study [32 patients]; SMD = −0.62; 95% CI −1.13 to −0.12)." (PMID 30116031, 2019). "In the majority of patients with paranoid schizophrenia, the basic CSF parameters were normal or showed non-specific changes, such as a blood-CSF barrier dysfunction (40%) as indicated by elevated albumin CSF-serum quotient." (PMID 40754554, 2025). "Elderly Chinese men with schizophrenia have a higher percentage of smokers, and although smoking can reduce their plasma albumin levels, it does contribute to the prevention of negative symptoms." (PMID 38462585, 2025). "Analysis of substrate specificity demonstrated that the IgGs of two different schizophrenia patients effectively hydrolyzed five histones and MBP, but did not hydrolyze other control proteins (human and bovine serum albumin, human milk lactoferrin, human lysozyme) under the same reaction conditions." (PMID 33008051, 2020). "However, none of the participants with schizophrenia or bipolar disorder in our sample had an increased albumin ratio." (PMID 23049916, 2012). "Accordingly, we found higher IBIL concentrations and higher IBIL/ALB in patients with AD, DLB, and GPI, but not in VD or elderly schizophrenia patients." (PMID 33013289, 2020). "Our study found that serum IBIL concentrations and the IBIL/ALB were significantly higher in patients with AD, DLB, or GPI, but not in cases of VD or in elderly schizophrenia patients." (PMID 33013289, 2020).
cardiac arrest (33 papers, 2014 to 2025). Cessation of breathing and/or cardiac function. "The higher albumin level at admission to ICU is associated with lower mortality in cardiac arrest patients." (PMID 34007754, 2021). "The higher albumin level at admission to the ICU was associated with lower mortality in patients with cardiac arrest." (PMID 34007754, 2021). "Consequently, studies have demonstrated that a decrease in serum albumin levels is linked to higher mortality rates following cardiac arrest." (PMID 37373829, 2023). "Relatively low serum albumin levels in the early phase may be associated with in-hospital mortality of resuscitated patients after cardiac arrest." (PMID 36579497, 2022). "Another study of 2414 patients admitted to the ICU concluded that the higher the albumin levels at the time of intake, the lower the mortality rate was in patients with cardiac arrest." (PMID 38541144, 2024). "The exploration of the ratio of inverse changes arising from distinct mechanisms in two independent predictors, specifically lactate and albumin, holds the potential for significant benefits in prognosticating the outcomes of patients following cardiac arrest." (PMID 37373829, 2023). "Medline, EMBASE, and the Cochrane Library were systematically searched until 4 July 2022, for studies on post-cardiac arrest patients and involving measurement of early phase albumin levels and assessment of in-hospital mortality or neurologic outcomes." (PMID 36579497, 2022). "The factors that associated the neurologic outcomes at hospital discharge for patients hospitalized after OHCA were age, witnessed cardiac arrest, initial shockable rhythm, and albumin, total cholesterol, pH, and PaCO2 levels." (PMID 35207721, 2022). "We aimed to evaluate early phase serum albumin levels in and outcomes of resuscitated patients after cardiac arrest." (PMID 36579497, 2022). "Low albumin levels were significantly correlated with a higher rate of cardiac arrest in this study." (PMID 34362025, 2021). "We aimed to investigate the importance of albumin level on admission, which is a widely available and simple test, to predict in-hospital mortality in cardiac arrest patients." (PMID 34007754, 2021). "Previous studies also demonstrated that poor nutrition and lower albumin levels were correlated with a higher rate of cardiac arrest and mortality." (PMID 34362025, 2021). "Few previous studies have investigated the relationship between albumin levels and prognosis in cardiac arrest patients." (PMID 34007754, 2021). "This study aimed to investigate the importance of albumin level, which is a widely available and simple test, to predict in-hospital mortality in cardiac arrest patients." (PMID 34007754, 2021). "The patients with out-of-hospital cardiac arrest over 19 years old and acquired laboratory data including calcium, ionized calcium, potassium, phosphorus, creatinine, albumin at emergency department (ED) arrival were included." (PMID 33045006, 2020). "In animal studies as evidence of this, albumin supplementation improves cerebral blood flow in cardiac arrest and resuscitation models." (PMID 32025402, 2019). "Cardiac arrest-induced inflammation could lead to increased RDW elevation and decreased albumin levels, which causes a significant increase in RAR." (PMID 39839831, 2024). "The comprehensive combination of lactate and albumin analysis can provide potential benefits for predicting the prognosis of patients with ROSC after cardiac arrest using the ratio of inverse change due to the different mechanisms of the two independent predictors." (PMID 37373829, 2023). "In cardiac arrest, vascular permeability for the cells and plasma solutes is increased as a common reaction, and albumin might leak out of the vessels." (PMID 34007754, 2021). "Their pre-arrest serum albumin levels were measured within 24 h before the cardiac arrest." (PMID 34017041, 2021).